RHOH (ras homolog family member H)
Description:
Negative regulator of hematopoietic progenitor cell proliferation, survival and migration. Critical regulator of thymocyte development and T-cell antigen receptor (TCR) signaling by mediating recruitment and activation of ZAP70. Required for phosphorylation of CD3Z, membrane translocation of ZAP70 and subsequent activation of the ZAP70-mediated pathways. Essential for efficient beta-selection and positive selection by promoting the ZAP70-dependent phosphorylation of the LAT signalosome during pre-TCR and TCR signaling. Crucial for thymocyte maturation during DN3 to DN4 transition and during positive selection. Plays critical roles in mast cell function by facilitating phosphorylation of SYK in Fc epsilon RI-mediated signal transduction. Essential for the phosphorylation of LAT, LCP2, PLCG1 and PLCG2 and for Ca(2+) mobilization in mast cells (By similarity). Binds GTP but lacks intrinsic GTPase activity and is resistant to Rho-specific GTPase-activating proteins. Inhibits the activation of NF-kappa-B by TNF and IKKB and the activation of CRK/p38 by TNF. Inhibits activities of RAC1, RHOA and CDC42. Negatively regulates leukotriene production in neutrophils.
Synonyms: ARHH; TTF; IMD129
Tractability: Antibody: its Gene Ontology location is reachable by antibodies, with high confidence; UniProt places it where antibodies can reach, with medium confidence. PROTAC: ubiquitination databases record sites on it.
Gene: Protein-coding gene on chromosome 4 (40,191,011 to 40,246,967, forward strand). Ensembl gene ENSG00000168421.
Subcellular location: Cytoplasm; Cell membrane
Subcellular location (Human Protein Atlas): Golgi apparatus; Vesicles
Pathways (Reactome):
Signal Transduction: RHOH GTPase cycle
Gene Ontology:
Molecular function: GTP binding; kinase inhibitor activity; protein binding; GTPase inhibitor activity; protein kinase binding; small GTPase binding; G protein activity; GTPase activity
Biological process: negative regulation of canonical NF-kappaB signal transduction; positive regulation of T cell differentiation; actin filament organization; regulation of DNA-templated transcription; T cell differentiation; mast cell activation; small GTPase-mediated signal transduction
Cellular component: cytoplasm; plasma membrane; immunological synapse
Genetic constraint (gnomAD): Loss-of-function variants: 6 observed, 14.05 expected, observed/expected ratio (o/e) 0.43, 90% interval 0.23 to 0.84. The upper end of that interval is the gene's LOEUF score, 0.84, which puts it in group 3 of 6, group 1 being the genes least tolerant of losing a copy. Missense variants: 147 observed, 255.71 expected, observed/expected ratio (o/e) 0.57, 90% interval 0.5 to 0.66. Synonymous variants: 117 observed, 108.72 expected, observed/expected ratio (o/e) 1.08, 90% interval 0.93 to 1.25.
Gene-disease validity (ClinGen):
ClinGen rates the evidence that RHOH causes each of these diseases.
epidermodysplasia verruciformis, susceptibility to, 4 (autosomal recessive): Moderate.
Cancer hallmarks: suppression of growth (promotes); invasion and metastasis (suppresses); escaping programmed cell death (suppresses)
Homologues: Orthologues: chimpanzee RHOH (99% identical), macaque RHOH (99% identical), rabbit RHOH (97% identical), dog RHOH (97% identical), mouse Rhoh (97% identical), guinea pig RHOH (96% identical), rat Rhoh (96% identical), pig RHOH (94% identical), tropical clawed frog rhoh (77% identical), zebrafish rhoh (75% identical). Paralogues in human: CDC42 (40% identical), RHOV (40% identical), RAC3 (39% identical), RAC1 (38% identical), RND3 (38% identical), RAC2 (37% identical), RHOQ (37% identical), RHOU (37% identical), RHOJ (37% identical), RHOA (36% identical), RHOB (36% identical), RHOC (36% identical), and 10 more.
Diseases named in the same sentence as RHOH in open-access papers:
RHOH is named in the same sentence as 70 diseases in open-access papers, as found by Europe PMC text mining. Sharing a sentence is not in itself a finding about the gene and the disease. The quoted sentences say what the papers report.
lymphoma (9 papers, 2007 to 2024). A malignant (clonal) proliferation of B- lymphocytes or T- lymphocytes which involves the lymph nodes, bone marrow and/or extranodal sites. "The involvement of RhoH aSHM mutation in lymphoma progression is highly correlated with the mRNA levels of activation-induced deaminase (AID) enzyme, wherein low levels of AID mRNA expression result in the low frequency of RhoH aSHM." (PMID 33923951, 2021). "We found a variant causing a g→c change at nucleotide 175 in the 5'-UTR of RhoH, a gene prone to aberrant hypermutation activity in lymphomas." (PMID 17201911, 2007). "These chromosomal alterations of RhoH gene result in the aberrant expression of RhoH, and disruption of RHOH has been reported in various lymphoma cases." (PMID 33923951, 2021). "Overall, a clear signaling network related to RHOH deregulation in human lymphomas is still missing and needs further studies." (PMID 31248017, 2019). "More specifically, in human lymphomas recurrent somatic mutations have been reported only for the GTPase RHOA and for the atypical GTPase RHOH, whereas somatic mutations affecting RAC proteins or CDC42 have been described in solid tumors." (PMID 31248017, 2019). "In this review we present the latest advances in the field with particular focus on the role of the most studied typical RHO GTPases such as CDC42, RAC1, and RHOA and the atypical RHOH in the initiation or progression of human lymphomas." (PMID 31248017, 2019). "As expected, the highest RhoH expression levels were found in T- and B-cell-derived cancers including lymphoma and leukemia cell lines." (PMID 29510700, 2018). "Since then, RhoH has been implicated in human cancer as the gene is subject to somatic hypermutation and by the detection of RHOH as a translocation partner for LAZ3/BCL6 or other genes in human lymphomas." (PMID 18823547, 2008). "Aberrant somatic mutation of RHOH has originally been described for diffuse large B-cell lymphoma (DLBCL), a group of aggressive lymphomas with heterogeneous clinical outcome." (PMID 18823547, 2008). "In addition, data generated in lymphoma cells derived by murine Bcl6-Rhoh ko Tg mice suggested that RHOH can be involved in DLBCL development by regulating BCL6 expression." (PMID 31248017, 2019). "Nevertheless, RhoH-deficient animals did not develop lymphomas or show other B cell malignancies, which is a discrepancy that shows the limit of the animal model." (PMID 20738848, 2010). "RhoH-deficient mice did not develop lymphomas and had no obvious defects in HSC maintenance, but they showed impaired T-cell differentiation attributed to defective T-cell receptor signalling." (PMID 18823547, 2008). "However, RhoH aberrant somatic hypermutation (aSHM) rarely occurs in Burkitt lymphoma and follicular lymphoma (FL), suggesting that RhoH aSHM selectively occurs depending on the type of lymphoma and most probably in more aggressive types." (PMID 33923951, 2021). "RhoH aSHM was found to contribute to cancer progression from FL or chronic lymphocytic leukaemia (CLL) to DLBCL, indicating that deregulation of RhoH protein expression is highly related to higher-grade lymphomas and might act as an important prognostic marker." (PMID 33923951, 2021). "However, RhoH-deficient mice did not develop lymphomas or showed obvious defects in haematopoiesis." (PMID 18823547, 2008).
acute myeloid leukaemia (6 papers, 2008 to 2024). "In addition, abnormal quantitative levels of RHOH expression have been linked to the pathogenesis of hairy cell leukemia, acute myeloid leukemia, chronic lymphocytic leukemia, and prostate cancer." (PMID 35845268, 2021). "Others loci are associated with hematological disorders such as CEBPA, FOXP1, MECOM and RHOH which promotes Acute myeloid leukemia, diffuse large B-cell lymphoma, myeloproliferative neoplasm and B-cell chronic lymphocytic leukemia respectively." (PMID 31105870, 2019). "Underexpression of RhoH is found in hairy cell leukaemia and acute myeloid leukaemia." (PMID 18823547, 2008). "Interestingly, these findings could be reproduced using human THP-1 cells as a model system for acute myeloid leukaemia, where low RhoH levels are known to be an unfavourable prognostic marker." (PMID 20738848, 2010). "In Hairy Cell Leukaemia (HCL) and Acute Myeloid Leukaemia (AML), RhoH was found to be underexpressed at the protein level." (PMID 20738848, 2010). "Two recent publications highlight the fact that RhoH is underexpressed in hairy cell leukaemia (HCL) and acute myeloid leukaemia (AML), respectively." (PMID 18823547, 2008). "The hematopoietic GTPase RhoH acts as a negative regulator for IL-3-induced signals by controlling STAT activity and IL-3 Receptor α expression, ultimately resulting in the preferential activation of STAT1 and decreased cell proliferation in acute myeloid leukemia." (PMID 38702781, 2024).
diffuse large B-cell lymphoma (6 papers, 2008 to 2025). "RHOH was considered as proto‐oncogene in diffuse large B‐cell lymphoma, suggesting that overexpression of RHOH was associated with poor prognosis." (PMID 36710485, 2023). "Subsequently, RhoH has been found to be mutated in multiple myeloma and diffuse large B cell lymphomas (DLBCL) and in AIDS-associated NHL, although the pathophysiological relevance of these findings are still unknown." (PMID 21103055, 2010). "RhoH, an hematopoietic-specific Rho GTPase,was first identified as a fusion transcript with Bcl-6 in B-cell diffuse large cell lymphoma." (PMID 21103055, 2010). "In patients with a clinically normal immune function, the Epstein-Barr virus is predominantly negative, and the mutation frequency of proto-oncogenes, including Pim-1, RhoH/TTF and c-Myc, is two to five-fold higher than in patients with extracranial diffuse large B-cell lymphomas." (PMID 25789045, 2015). "The authors found that in the course of transformation from the rather indolent follicular lymphoma into the more aggressive diffuse large B-cell lymphoma, LAZ3/BCL6 translocations with RHOH were widespread." (PMID 18823547, 2008). "This is in contrast to results published by the same group on the impact of aberrant SHM of RHOH in diffuse large B-cell lymphoma, where such a link was not detectable." (PMID 18823547, 2008).
breast carcinoma (4 papers, 2016 to 2024). "We show here that RhoH is in fact expressed in a wide range of prostate and breast cancer cell lines and human cancers." (PMID 29510700, 2018). "The 8 prostate cancer cell lines and 58 breast cancer cell lines in the CCLE database expressed RhoH mRNA at a wide range of levels." (PMID 29510700, 2018). "Similar to PC3 cells, RhoH depletion increased spread area in two other cell lines that express RhoH: T47D breast cancer cells and LNCaP prostate cancer cells (unpublished data)." (PMID 29510700, 2018). "Quantitative real-time PCR (qPCR) analysis showed that, of the cancer cell lines analysed, RhoH mRNA levels were highest in T47D breast cancer cells followed by LNCaP and PC3 prostate cancer cells, whereas RhoH mRNA was very low or not detected in a variety of other cancer cell lines." (PMID 29510700, 2018).
lung carcinoma (4 papers, 2017 to 2023). "We revealed the difference between tumor and normal lung tissue in RHOH methylation based on TCGA database and verified it with Asian population samples, indicating that RHOH may be a potential target for lung cancer treatment." (PMID 36710485, 2023).
melanoma (4 papers, 2016 to 2021). A malignant, usually aggressive tumor composed of atypical, neoplastic melanocytes. "The RhoH transcription level of melanoma cells was significantly lower than that of MC." (PMID 28404912, 2017).
prostate carcinoma (4 papers, 2018 to 2023). A carcinoma that arises from epithelial cells of the prostate gland. "We investigated the relevance of RhoH expression in prostate cancer by analysing existing gene expression data associated with clinical parameters of disease progression." (PMID 29510700, 2018). "This indicates that increased RhoH levels may be associated with poor prognosis in patients with prostate cancer." (PMID 29510700, 2018). "Previous expression analysis implied that RhoH is expressed only in haematopoietic cells, and thus it was surprising that it had a phenotype in a prostate cancer cell line." (PMID 29510700, 2018). "Our analysis of prostate cancer gene expression data suggests that higher RhoH expression correlates with more rapid cancer progression, and thus the role of RhoH in prostate cancer warrants further investigation." (PMID 29510700, 2018). "It was reported that RHOH could promote migration of prostate cancer cells, and the prognosis of prostate cancer patients with high expression of RHOH was relatively poor." (PMID 36710485, 2023). "For example, RHOH expression levels correlate with prostate cancer progression." (PMID 33255394, 2020). "We describe a novel role for RhoH in prostate cancer cell migration." (PMID 29510700, 2018). "Our results also suggest that RhoH expression levels correlate with prostate cancer progression." (PMID 29510700, 2018). "Analysis of data from a cohort of patients with prostate cancer from the Memorial Sloan Kettering Cancer Center (MSKCC) showed that high levels of RhoH in the tumour samples correlate with decreased recurrence-free survival (RFS) (determined by measuring prostate-specific antigen (PSA) levels)." (PMID 29510700, 2018). "High RhoH expression in samples from prostate cancer patients correlates with earlier relapse." (PMID 29510700, 2018). "Thus, under certain conditions, RhoH is a positive regulator of T cell migration, similar to our observations in prostate cancer cells." (PMID 29510700, 2018).
Leukaemia (3 papers, 2008 to 2021). "Information on the role of RhoH in the pathogenesis of leukaemia is limited, but it is known to reduce HCL proliferation and transendothelial migration in a xenograft mouse model of HCL." (PMID 33923951, 2021). "Nevertheless, the recent finding that RHOH is underexpressed in certain types of leukaemia implies that RhoH expression levels are a crucial factor in protection from the development of haematopoietic malignancies." (PMID 18823547, 2008). "Leukaemia associated with an underexpression of RHOH mRNA are depicted without colour, as the mechanism of deregulation has not yet been established." (PMID 18823547, 2008). "However, because RhoH expression can be regulated by phosphorylation, lysosomal degradation and transcriptional repression by the AP−1 transcription factor, JunD, either of these regulations may be impaired in leukaemia." (PMID 33923951, 2021).
B-cell chronic lymphocytic leukemia (2 papers, 2019 to 2022). "B-cell receptor signaling is intact in RhoH-deficient cells, however B-cell chronic lymphocytic leukemia is dependent on RhoH." (PMID 35529883, 2022).
B-cell lymphoma (2 papers, 2025). "Both IGH and RHOH are highly expressed in normal B cells indicating that the merger of the BCL6 SS domain with SE regions potentially represents a functional explanation for the aberrant upregulation of BCL6 in B-cell lymphoma." (PMID 40998810, 2025). "Both IGH and RHOH are highly expressed in normal B cells, indicating that the merger of the BCL6 SS domain with SE regions represents a potential functional explanation for the aberrant upregulation of BCL6 in B-cell lymphoma." (PMID 40631184, 2025).
colorectal cancer (2 papers, 2013 to 2020). A primary or metastatic malignant neoplasm that affects the colon or rectum. "Examples discussed in this review include Cdc42, Rac1, RhoA, RhoC and RhoH activation of oncogenic STAT3, and in some cases STAT5, in a range of cancers including but not limited to: breast, bladder, gastric, cervical, myeloid, pancreatic, hepatocellular, head and neck, and colorectal cancer." (PMID 32915198, 2020).
follicular lymphoma (2 papers, 2008 to 2021). Follicular lymphoma is a form of non-Hodgkin lymphoma characterized by a proliferation of B cells whose nodular structure of follicular architecture is preserved. "Here, the accumulation of novel mutations in RHOH and other gene loci (PIM1, PAX5, MYC) was found to be associated with transformation of follicular lymphoma and chronic lymphocytic leukaemia to DLBCL." (PMID 18823547, 2008).
hairy cell leukaemia (2 papers, 2008 to 2021). "Aside from aSHM, low levels of RhoH were also observed in several patients with hairy cell leukaemia (HCL), acute myeloid leukaemia (AML) and CLL but the mechanism involved in this protein levels deregulation is still unknown." (PMID 33923951, 2021). "The recent finding that overexpression of RhoH in hairy cell leukaemia reduces the transformation potential might stimulate a new interest in the functioning of RhoH on a molecular level." (PMID 18823547, 2008).
Immunodeficiency (2 papers, 2021 to 2025). Failure of the immune system to protect the body adequately from infection, due to the absence or insufficiency of some component process or substance. "Among the rare small Rho GTPases that receive much attention is RhoH as it is associated with several diseases, such as B cell malignancies, immunodeficiency and autoimmune diseases." (PMID 33923951, 2021). "However, deregulated RhoH protein expression either through aSHM, lysosomal degradation, or transcriptional repression, has been associated with poor outcomes of B cell malignancies and immune-related diseases, such as immunodeficiency and autoimmune diseases." (PMID 33923951, 2021). "Considering the importance of RhoH in regulating TCR and BCR signalling pathways, much effort has been exerted on targeting RhoH to control diseases derived from abnormal T and B cell activation, such as cancer, immunodeficiency disorders and autoimmune diseases." (PMID 33923951, 2021). "Importantly, no mutations were detected in other known EV-associated or immunodeficiency-related genes, such as RHOH, IL7, CORO1A, STK4, DOCK8, or CARMIL2, supporting the notion that the identified TMC6 and TMC8 variants may represent the primary genetic contributors in this case." (PMID 40534698, 2025).
multiple myeloma (2 papers, 2008 to 2010). "A different RHOH translocation was found in a case of multiple myeloma (or plasma cell myeloma)." (PMID 18823547, 2008).
non-Hodgkin lymphoma (2 papers, 2008 to 2024). Distinct from Hodgkin lymphoma both morphologically and biologically, non-Hodgkin lymphoma (NHL) is characterized by the absence of Reed-Sternberg cells, can occur at any age, and usually presents as a localized or generalized lymphadenopathy associated with fever and weight loss. "RHOH encodes a member of the Ras superfamily of guanosine triphosphate (GTP)-metabolizing enzymes and has been implicated in non-Hodgkin’s lymphoma." (PMID 38517886, 2024).
primary immunodeficiencies (2 papers, 2016 to 2021). "Aberrant protein expression of RhoH has been implicated not only in B cell malignancies but also in immune-related diseases, such as primary immunodeficiencies, systemic lupus erythematosus and psoriasis, wherein its involvement may provide the link between immune-related diseases and cancer." (PMID 33923951, 2021). "We report a novel primary immunodeficiency, and a differential molecular diagnosis to CXCR4‐,DOCK8‐,GATA2‐,MAGT1‐,MCM4‐,STK4‐,RHOH‐,TMC6‐, and TMC8‐related diseases." (PMID 27896283, 2016).
T cell lymphomas (2 papers, 2008 to 2021). "Nonetheless, despite the obvious role of RhoH in T cell development, RhoH involvement in T cell-specific malignancies, such as in T cell lymphomas, is not well understood." (PMID 33923951, 2021). "Despite this important role of RhoH in T-cell development, it has not been addressed so far whether RhoH is also involved in T-cell specific malignancies, for example in T-cell lymphomas." (PMID 18823547, 2008).